LEP (leptin)
Diseases named in the same sentence as LEP in open-access papers (continued):
Sharing a sentence is not in itself a finding about the gene and the disease.
melanoma (47 papers, 2011 to 2025). A malignant, usually aggressive tumor composed of atypical, neoplastic melanocytes. "Epidemiological studies demonstrated that a high level of leptin in serum is positively correlated with the risk of melanoma, while in vivo, injection of leptin into melanoma-bearing mice led to the increase in weight and size of the tumor." (PMID 33430277, 2021). "We observed a signature biomarker change in the serum associated with EE-induced inhibition of melanoma including decreased leptin, increased adiponectin, and decreased IGF-1." (PMID 24587106, 2014). "Clinical reports link elevated serum leptin levels to an increased risk of certain cancers including prostate, breast, and melanoma." (PMID 24587106, 2014). "Just one epidemiological study demonstrated that high serum leptin was positively correlated with melanoma risk." (PMID 21338489, 2011). "One epidemiological study reported that high serum leptin was positively correlated with melanoma risk." (PMID 21338489, 2011). "In conclusion, our observations indicate that leptin causes melanoma growth likely through increased NO production and circulating EPC numbers and consequently vasculogenesis." (PMID 21338489, 2011). "Furthermore, a high level of leptin in serum is associated with increased risk of melanoma in humans, while in mice, it is related to greater weight and size of melanoma tumors." (PMID 37481560, 2023). "Intriguingly, reduced melanoma growth was found in lean, pair fed leptin deficient ob−/− mice, compared to tumors from lean wild type or ob+/− mice, which have similar body weights but higher leptin levels." (PMID 24202338, 2013). "In conclusion, our observations indicate that leptin causes melanoma growth." (PMID 21338489, 2011). "However, leptin deficiency significantly attenuates melanoma growth and its high level may accelerate this process." (PMID 34068679, 2021). "Furthermore, it was suggested that leptin might cause melanoma growth through increased NO production and circulating endothelial progenitor cell (EPC) numbers and consequently induced tumor angiogenesis." (PMID 24202338, 2013). "We have shown in SM patients that the chronic inflammatory state is modulated by the metabolic imbalance, and that among the adipokines, leptin (LEP) is increasing with melanoma staging and the age of the patients." (PMID 41470117, 2025). "In agreement, CMM patients have higher circulating leptin levels at diagnosis and melanoma tumour growth is higher in obese mice with high leptin levels and lower in lean leptin-deficient mice with restricted diet." (PMID 38783251, 2024). "The adipocytes in obese individuals produce less adiponectin, which is anti-neoplastic, and more leptin and cytokines, including interleukin 6, interleukin 8, and transforming growth factor-β, which can increase melanoma and NMSC growth and metastasis." (PMID 37777736, 2023). "The triterpenoids at a non-toxic concentration of 0.1 μM significantly inhibited the mitogenic effect of leptin in B16 melanoma cells also, showing an efficacy similar to that observed in neuroblastoma cells." (PMID 37895840, 2023). "This was based on strong inhibitory actions (>90%) on VEGF (major angiogenesis coordinator), FasL (inducer of anticancer T-cell apoptosis at the vascular border), and leptin (stimulator of angiogenesis and overall accelerator of melanoma growth)." (PMID 35450036, 2022). "Leptin has been identified as a potent metabolic reprogramming agent, and melanoma cells express leptin-induced superior metabolic function and memory phenotype in T cells within the TME." (PMID 35203357, 2022). "Together with leptin, it increases the proliferation of melanoma cells through the Akt signaling pathway." (PMID 34068679, 2021). "While leptin was undetectable in medium from mouse melanoma cells, in vitro studies indicate that it enhances the proliferation of cancer cells." (PMID 34068679, 2021).
melanoma (continued). "Importantly from a therapeutic perspective, the effects could be recapitulated with a modified oncolytic vaccinia virus encoding leptin and injected directly into poorly immunogenic melanoma and pancreatic tumor models, which conferred a significant survival advantage." (PMID 33927722, 2021). "It was shown that both leptin and resistin, two hormones released by adipocytes, stimulate melanoma cell proliferation in vitro by regulating FASN as well as the AKT-based signal transduction pathway." (PMID 33430277, 2021). "Clinical data suggest that leptin has a role in both melanoma growth and metastasis and this is supported in preclinical studies in which leptin was found to increase melanoma cell proliferation and tumor growth." (PMID 32549336, 2020). "Using these experimental results authors engineered oncolytic viruses to induce leptin expression in melanoma cells and in mouse experimental model where completely regressed tumors were achieved and T memory populations was induced." (PMID 32509589, 2020). "The serum level of leptin was significantly higher in the SN-positive group compared to the SN-negative group of melanoma subjects." (PMID 33008429, 2020). "An in vitro model showed that IH-induced increases of TGF-β1 expression in melanoma cells is attenuated in the presence of high leptin levels." (PMID 32968152, 2020). "In the OSA patients overall, leptin levels weakly correlated with melanoma growth rate (r = 0.192, p = 0.008) and Breslow index (r = 0.140, p = 0.054)." (PMID 32968152, 2020). "Upon leptin and resistin treatment using A375 melanoma cell line, fatty acid synthase (FASN) and caveolin 1 (Cav-1), respectively, were found increased." (PMID 32509589, 2020). "Leptin also enhances mitochondrial metabolism in CD8+ T cells, and oncolytic virus-mediated expression of leptin in the TME improved CD8+ T cell function in a mouse model of melanoma." (PMID 33170123, 2020). "IH exposures in vitro increased bioactive TGF-β1 levels in the culture supernatant of melanoma cells subjected to the lowest leptin concentration, while such effect disappeared with the higher leptin concentration." (PMID 32968152, 2020). "Leptin and its functional receptor was detected in human melanoma cell lines as well as in histological sections in melanomas." (PMID 33260746, 2020). "In our study, the serum levels of leptin were increased in mice fed a high-fat diet; this is one possible explanation for the increased growth rate of melanomas explanted into mice in this cohort." (PMID 31528182, 2019). "The present study is aimed at unraveling the specific role of leptin and resistin in melanoma growth and the chemotherapeutic outcome using appropriate in vitro and in vivo approaches." (PMID 29568521, 2018). "To corroborate the involvement of leptin in melanoma growth and in the outcome of DTIC treatment, we employed ob/ob and db/db mice." (PMID 29568521, 2018). "In the present study, we observed that leptin and resistin cause impairment in the effect of DTIC on melanoma cells in vitro." (PMID 29568521, 2018). "Both leptin and resistin not only enhance proliferation of melanoma cells but also are involved in impairing the therapeutic efficacy of DTIC." (PMID 29568521, 2018). "In the present study, we investigated the specific role of leptin and resistin in melanoma cell growth, proliferation, and the outcome of DTIC-based chemotherapy." (PMID 29568521, 2018). "Our results clearly indicated that leptin and resistin partly contribute to melanoma progression and in impairing the outcome of dacarbazine therapy." (PMID 29568521, 2018). "Further, it was observed that leptin and resistin impaired the response of melanoma cells to DTIC via upregulation of heat shock protein 90 (Hsp90) and P-glycoprotein (P-gp) respectively." (PMID 29568521, 2018).
melanoma (continued). "Collectively, these data suggest that both leptin and resistin partly play a crucial role in melanoma growth and adversely affect the chemotherapeutic outcome by modulating the molecules which are involved in tumor growth and drug resistance." (PMID 29568521, 2018). "This led us to explore another possible mechanism by which leptin contributes to the impaired DTIC action on melanoma cells." (PMID 29568521, 2018). "Higher IC50 value of DTIC was observed in melanoma cells grown in the serum of db/db mice (8410 μM), which contains very high circulatory leptin, as compared to control (1830 μM)." (PMID 29568521, 2018). "In a nutshell, this study highlights the role of leptin and resistin in melanoma growth, and impairment in the chemotherapeutic outcome." (PMID 29568521, 2018). "A study of melanoma patients found significantly higher leptin levels in those with positive sentinel node biopsies." (PMID 27525031, 2016). "In this study we investigated the effect of pharmacological blockade of leptin in the same mouse model of melanoma." (PMID 24587106, 2014). "Our leptin replacement data also showed that exogenous leptin increased melanoma mass in ob/ob mice by 140% compared to pair-fed saline-infused mice with identical body weight and fat mass." (PMID 24587106, 2014). "Our objectives in the present study were to examine the effects of leptin on melanoma growth, circulating EPCs number and plasma levels of nitric oxide metabolites (NOx)." (PMID 21338489, 2011). "The mechanisms by which leptin promotes melanoma growth likely involve increased NO production and circulating EPC numbers and consequently vasculogenesis." (PMID 21338489, 2011). "Given the previously reported stimulating effects of leptin on various malignancies, including NC-derived melanoma and pheochromocytoma, first, we questioned whether leptin has pro-tumor functions in neuroblastoma." (PMID 37895840, 2023). "In addition, adiponectin, with characteristic low levels in obese patients, has the opposite effect, analogous to leptin and resistin in melanoma." (PMID 35334544, 2022). "The autocrine loop of leptin has also been suggested in studies on human nevi and melanomas." (PMID 34068679, 2021). "Moreover, the treatment of the A375 melanoma cells with leptin deteriorates the reaction on the chemotherapeutic drug-dacarbazine." (PMID 34068679, 2021). "Other studies report the existence of a correlation between plasma leptin level and melanoma." (PMID 34068679, 2021). "The promotion of melanoma growth by leptin was also affirmed in research on mice." (PMID 34068679, 2021). "The researchers also reported that increased serum leptin levels may have an impact on melanoma progression and predict sentinel node (SN) metastasis." (PMID 33008429, 2020). "The authors assumed that inhibition of the leptin/ LepR system could enhance the efficacy of multiple therapeutic approaches in the therapy of melanoma." (PMID 33008429, 2020). "Leptin and resistin enhance proliferation of melanoma cell lines and hinder DTIC efficacy." (PMID 32509589, 2020). "Adipocytes are lipid-rich, highly secretory cells that release lipids, chemokines, inflammatory factors and adipokines including leptin, all of which could impact on melanoma progression." (PMID 32549336, 2020). "Moreover, the results of our in vitro model confirmed that intermittent hypoxia-induced elevations in active TGF-β1 expression in melanoma cells are attenuated by higher leptin levels." (PMID 32968152, 2020). "Moreover, we explored the leptin effect on TGF-β1 released by melanoma cells under intermittent hypoxia in an in vitro model of OSA." (PMID 32968152, 2020). "The group of Malvi showed that leptin administration may impair the efficacy of dacarbazine therapy of melanoma in obese ob/ob and db/db mice models." (PMID 33008429, 2020).
melanoma (continued). "In human WM793 and WM35 melanoma cell lines, leptin treatment activated the MAPK pathway and enhanced cell proliferation, suggesting that leptin may act as a melanoma growth factor, and may contribute to the uncontrolled proliferation of these cells." (PMID 33260746, 2020). "Moreover, the in vitro melanoma cell culture model showed that the IH-induced increase of active TGF-β1 expression is attenuated by the presence of higher leptin levels." (PMID 32968152, 2020). "However, future studies investigating leptin signaling in lymphocytes by using leptin receptor knockout mice will be important to evidence this relationship in melanoma models." (PMID 31528182, 2019). "Nonetheless, our in vitro studies (especially treatment of melanoma cells with leptin and resistin, as well as their immune-depletion) demonstrate that these adipokines critically affect melanoma growth, and the chemotherapeutic outcome, by modulating melanoma promoting proteins." (PMID 29568521, 2018). "However, the specific role of leptin in modulating melanoma cell proliferation and the chemotherapeutic outcome is obscure." (PMID 29568521, 2018). "To confirm whether FASN and Hsp90 are involved in leptin-induced impairment in the response of melanoma cells to DTIC, we used their respective inhibitors." (PMID 29568521, 2018). "We then engineered melanoma cell lines to locally secrete leptin." (PMID 30400822, 2018). "Therefore, we analyzed the involvement of Hsp90 and checked the expression of Hsp90 in melanoma cells upon treatment with leptin." (PMID 29568521, 2018). "To get insights into the role of leptin and resistin in causing attenuation in the response to DTIC, we intended to analyze the status of FASN and Cav-1 which are upregulated in melanoma in the obese (HFD) mice, and are known to be involved in resistance to cancer chemotherapy." (PMID 29568521, 2018). "Although, our in vitro results established the fact that both leptin and resistin are involved in impairing the response of melanoma cells to DTIC, it is difficult to validate their role in vivo due to lack of resistin knockout animals as well as resistin neutralizing antibody." (PMID 29568521, 2018). "However, cycloheximide chase experiment confirms that leptin and resistin cause the stabilization of FASN and Cav-1 protein levels respectively in melanoma cells." (PMID 29568521, 2018). "Furthermore, earlier data have shown that adipocyte numbers in the bone marrow affect leptin levels, which were shown to accelerate melanoma growth." (PMID 27049717, 2016). "Leptin is the primary peripheral mediator of this anticancer effect in a mouse model of melanoma." (PMID 24587106, 2014). "Additionally, obese MC4R−/− (melanocortin receptor 4 knockout) mice with high plasma leptin levels showed higher development of melanoma compared to lean controls." (PMID 24202338, 2013). "There is very little previous information on the relationship between leptin and melanoma." (PMID 21338489, 2011). "Thus, higher sensitivity to oestrogens in women, potentially counterbalancing the pro-oncogenic properties of leptin, may explain the more favourable melanoma outcomes in women compared to men and the null association with BMI in women." (PMID 38783251, 2024). "We examined whether adipocytes cocultured with melanoma cells demonstrate decreased expression of adipocyte differentiation markers such as leptin, resistin, adiponectin, and fatty acid binding protein (FABP4) by assessing the expression of these genes in the cells." (PMID 37481560, 2023). "In addition, elevation of VEGF-A expression by leptin was reported in melanoma." (PMID 33799880, 2021). "Leptin may act as a pro-tumoral factor in various cancer types and stimulate melanoma growth." (PMID 34068679, 2021). "Moreover, hyperinsulinemia and insulin resistance may promote melanoma growth mediated by insulin-like growth factor-I and leptin because patients with diabetes had a worse prognosis." (PMID 34068679, 2021).
melanoma (continued). "According to the literature, increased leptin concentration may accelerate the growth of melanoma." (PMID 33008429, 2020). "Additionally, to verify the involvement of leptin in modulating the response of melanoma cells to DTIC therapy, B16F10 cells were cultured in the medium containing serum of genetically obese mice strains ob/ob (leptin deficient) or db/db (leptin receptor deficient)." (PMID 29568521, 2018). "Thus, the mutual involvement of FASN and Hsp90 could contribute to the unresponsiveness of melanoma cells to DTIC in the presence of leptin." (PMID 29568521, 2018). "Moreover, our data show that depletion of leptin and resistin from the serum collected from obese mice resulted in the improved response of melanoma cells as compared to the undepleted serum suggestive of their role in modulating the response of melanoma cells to DTIC." (PMID 29568521, 2018). "Moreover, it has been shown that leptin directly accelerated melanoma tumor growth in mice." (PMID 21338489, 2011). "In one study, melanoma-infiltrating CD8+ T cells were found to exhibit higher LepR levels than cells present in lymphoid tissue, and tumors engineered to express leptin grew more slowly, leading to improved survival." (PMID 33927722, 2021). "In a recent mouse model using ob/ob and db/db strains the roles of leptin and resistin in the dacarbazine (DTIC) therapy in melanoma was reported." (PMID 32509589, 2020). "To assess the effects of leptin in the tumor microenvironment, we generated an aggressive PTEN/BRAF melanoma line overexpressing leptin, as well as an oncolytic strain of Vaccinia virus engineered to induce tumor-specific secretion of leptin." (PMID 30400822, 2018). "ob/ob and db/db mouse models were used in this study to evaluate the role of leptin and resistin towards the outcome of dacarbazine (DTIC) therapy in melanoma." (PMID 29568521, 2018). "Here, we have shown the role of important adipokines leptin and resistin in growth and the outcome of DTIC therapy in melanoma." (PMID 29568521, 2018). "In contrast, a more recent study used the same mouse melanoma cell line implanted into C57BL/6J mice, showed a significant increase of tumor growth (188%) after exogenous leptin supply." (PMID 24202338, 2013). "High leptin levels in obese mice drive PD-1-mediated T-cell exhaustion in melanoma, and a lack of leptin signaling restores T-cell function." (PMID 39402302, 2024). "Leptin and resistin are both secreted by adipocytes and affect synthesis of FASN (fatty acid synthase) and the activation of the AKT-based signal transduction pathway, thus promoting the proliferation of melanoma cells." (PMID 37481560, 2023). "On the other hand, the VEGF and ObR expression in mice melanomas was correlated with tumor size but not with the host leptin level." (PMID 34068679, 2021). "The local administration adjacent to tumor of low-dose 2.17-mAlb remarkably slowed the melanoma growth and reduced melanoma mass by 33% without affecting weight and food intake showing that the central action of leptin was not blocked." (PMID 34356668, 2021). "These earlier observations are consistent with the inverse effect of exercise on leptin levels and the percentage of Treg cells that we also observed in the mice lacking melanoma." (PMID 31528182, 2019). "Although LEP-based targeting therapies have not yet been fully applied, LEP has already been identified as a potent metabolic reprogramming agent to support antitumor responses in aggressive melanomas." (PMID 40407808, 2025). "We noticed that mature adipocytes express a high level of selected adipokines (leptin, adiponectin, resistin), lipid transport protein (FABP4), and enzymes related to lipid synthesis (FADS, SC4MOL, FASN), while their levels decrease in adipocytes cocultured with melanoma cells." (PMID 37481560, 2023).